VSIR (V-set immunoregulatory receptor)
Description:
Immunoregulatory receptor which inhibits the T-cell response. May promote differentiation of embryonic stem cells, by inhibiting BMP4 signaling (By similarity). May stimulate MMP14-mediated MMP2 activation.
Synonyms: C10orf54; SISP1; VISTA; PP2135; GI24; B7-H5; B7H5; PD-1H; Dies1; DD1alpha
Tractability: Antibody: UniProt places it where antibodies can reach, with high confidence; its Gene Ontology location is reachable by antibodies, with high confidence; UniProt predicts a signal peptide or a membrane-spanning region. PROTAC: ubiquitination databases record sites on it; a small molecule that binds it is known.
Gene: Protein-coding gene on chromosome 10 (71,747,556 to 71,773,608, reverse strand). Ensembl gene ENSG00000107738.
Subcellular location: Cell membrane
Gene Ontology:
Molecular function: endopeptidase activator activity; enzyme binding; identical protein binding; protein binding
Biological process: negative regulation of CD4-positive, alpha-beta T cell proliferation; negative regulation of CD8-positive, alpha-beta T cell proliferation; negative regulation of interleukin-10 production; negative regulation of interleukin-17 production; negative regulation of tumor necrosis factor production; negative regulation of type II interferon production; positive regulation of cell migration; positive regulation of collagen catabolic process; positive regulation of endopeptidase activity; positive regulation of gene expression; positive regulation of regulatory T cell differentiation; zymogen activation; negative regulation of alpha-beta T cell activation; regulation of immune response
Cellular component: plasma membrane; membrane
Genetic constraint (gnomAD): Loss-of-function variants: 10 observed, 28.78 expected, observed/expected ratio (o/e) 0.35, 90% interval 0.21 to 0.59. The upper end of that interval is the gene's LOEUF score, 0.59, which puts it in group 2 of 6, group 1 being the genes least tolerant of losing a copy. Missense variants: 355 observed, 407.64 expected, observed/expected ratio (o/e) 0.87, 90% interval 0.8 to 0.95. Synonymous variants: 179 observed, 175.73 expected, observed/expected ratio (o/e) 1.02, 90% interval 0.9 to 1.15.
Homologues: Orthologues: chimpanzee VSIR (99% identical), macaque VSIR (96% identical), rabbit VSIR (82% identical), dog VSIR (80% identical), mouse Vsir (76% identical), tropical clawed frog vsir (25% identical), zebrafish si:dkey-22i16.9 (14% identical), zebrafish vsig8b (10% identical), zebrafish jam2b (9% identical), zebrafish jam2a (8% identical). Paralogues in human: IGSF11 (14% identical), CLMP (13% identical), CXADR (12% identical), ESAM (12% identical), VSIG2 (12% identical), GPA33 (11% identical), VSIG1 (11% identical), VSIG8 (11% identical), MXRA8 (11% identical), JAM2 (10% identical), MUC15 (9% identical), JAM3 (9% identical), and 2 more.
Diseases named in the same sentence as VSIR in open-access papers:
VSIR is named in the same sentence as 186 diseases in open-access papers, as found by Europe PMC text mining. Sharing a sentence is not in itself a finding about the gene and the disease. The quoted sentences say what the papers report.
breast carcinoma (36 papers, 2016 to 2025). "V-domain Ig suppressor of T cell activation (VISTA; encoded by VSIR), a checkpoint molecule expressed on naive CD4+ T cells, Tregs, and myeloid cell subsets, plays a multifaceted role in the context of breast cancer." (PMID 41550427, 2025). "We performed transient knockdown of the VSIR gene on the breast cancer cell line MDA-MB-468 to test the specificity of the VISTA antibody." (PMID 34064871, 2021).
autoimmune disease (27 papers, 2015 to 2025). A disorder resulting from loss of function or tissue destruction of an organ or multiple organs, arising from humoral or cellular immune responses of the individual to their own tissue constituents. "Notably, higher genetically predicted VSIR (encoding the immune checkpoint protein VISTA) was associated with decreased risk of T1D, providing human genetic support that complements existing animal-model evidence for VISTA’s protective role in autoimmune diseases." (PMID 41299435, 2025). "Two such examples are VSIR and P2RY12, both of which have existing functional work demonstrating their role in autoimmune disease." (PMID 41299435, 2025).
gastric cancer (27 papers, 2016 to 2026). A primary or metastatic malignant neoplasm involving the stomach. "The sequencing results suggest that the VSIR gene plays an important role in the development of gastric cancer, but the mechanism of action of this gene has rarely been studied." (PMID 39391750, 2025). "Our results revealed that the VSIR gene plays an important role in the development of gastric cancer." (PMID 39391750, 2025). "In subsequent experiments, we will further elucidate the mechanism by which the VSIR gene enables gastric cancer cells to generate immune escape and promote the formation and metastasis of gastric cancer through CCL4L2." (PMID 39391750, 2025). "Another scRNA‐seq database PKU‐scDVA21 also indicated that VSIR was predominantly expressed on monocytes/macrophages in gastric cancer." (PMID 38356419, 2024). "Furthermore, through precise sorting of gastric cancer cells, single-cell sequencing analysis revealed that the expression level of the VSIR gene in gastric cancer tissues was significantly greater than that in normal tissues." (PMID 39391750, 2025). "The results showed that the VSIR gene may constitute a new immune detection point and immunotherapy target for gastric cancer." (PMID 39391750, 2025). "Therefore, we need to explore the immunoregulatory mechanism of the VSIR gene in the formation of gastric cancer in detail." (PMID 39391750, 2025). "However, the mechanism by which the VSIR gene helps gastric cancer cells achieve immune escape during gastric cancer formation is still unclear, and further research is needed." (PMID 39391750, 2025). "We subsequently found numerous DEGs related to macrophages related to the development of gastric cancer, such as CST3, MS4A6A, CTSS, MPEG1, VSIR, and SDC2." (PMID 39391750, 2025). "The results showed that CD79A, DERL3, TNFRSF17, FKBP11, VSIR, SDC2, and other genes play vital regulatory roles in the formation of gastric cancer." (PMID 39391750, 2025). "Furthermore, we studied the VSIR mRNA level in TAMs to confirm that VISTA gene was expressed in these cells and that this protein did not come as a secreted protein from gastric cancer cells." (PMID 38356419, 2024). "Furthermore, we studied the VSIR mRNA level in TAMs to confirm that VISTA gene is expressed in these cells and that this protein did not come as a secreted protein from gastric cancer cells." (PMID 38356419, 2024). "We found that the expression pattern of VISTA‐encoding gene VSIR was distinguished from those of other genes, indicating VSIR (VISTA) might mediate an additional nonredundant immune‐checkpoint pathway in gastric cancer." (PMID 38356419, 2024). "In current study, we observed that VSIR showed a unique expression pattern distinct from other immune‐checkpoint genes in gastric cancer, which indicated that not all gastric cancer might have the same immunotherapeutic responsiveness." (PMID 38356419, 2024). "Furthermore, the Dies1/VSIR could trigger the differentiation of embryonic stem-cell and serve as an immune regulator through the BMP-pathway in gastric cancer." (PMID 36098688, 2022).
ovarian carcinoma (25 papers, 2019 to 2026). A malignant neoplasm originating from the surface ovarian epithelium. "In support of an antitumor tumor immune response, by targeting intracellular PD-L1 with a cell-penetrating antibody, the mRNA expression of PDCD1LG2, BIRC3, RELB, and VSIR was significantly decreased in ovarian cancer cells." (PMID 39996786, 2025). "We also found a significant positive correlation between PD-L1 (CD274) and the PDCD1LG2, BIRC3, RELB, and VSIR genes in the TCGA ovarian cancer-patient database." (PMID 39996786, 2025). "It has been demonstrated that upregulated VSIR on the tumor-infiltrating myeloid cells promotes tumor growth via suppressing T cell immunity, indicating that PXN might exhibit certain functions in immunotherapy for ovarian cancer." (PMID 36923874, 2023).
acute myeloid leukemia (23 papers, 2020 to 2025). Acute myeloid leukemia (AML) is a group of neoplasms arising from precursor cells committed to the myeloid cell-line differentiation. "High expression of VSIR mediates MDSC suppression of T-cell responses in patients with acute myeloid leukemia." (PMID 36163179, 2022). "VSIR is significantly upregulated in the tumor than normal samples in GBM, STAD, CHOL, LIHC, pancreatic adenocarcinoma (PAAD), brain lower-grade glioma (LGG), kidney renal clear cell carcinoma (KIRC), and acute myeloid leukemia (LAML) (P<0.001)." (PMID 35493077, 2022).
Autoimmunity (19 papers, 2015 to 2025). The occurrence of an immune reaction against the organism's own cells or tissues. "Here, we demonstrate that the effect of VSIR on autoimmunity, previously shown in animal models, is corroborated by human genetic data — an important predictor for clinical success of a targeting therapeutic." (PMID 41299435, 2025). "VISTA (VSIR) KO mice are prone to developing spontaneous autoimmunity, such as rheumatoid arthritis." (PMID 40385641, 2025).
lung cancer (15 papers, 2018 to 2025). A malignant neoplasm involving the lung. "Overexpression of YAP-5SA in MCF7 and BT474 cells, as well as H1437 and H1573 lung cancer cells, robustly upregulated VSIR and PD-L2 RNA expression." (PMID 40940864, 2025).
lymphoma (12 papers, 2021 to 2025). A malignant (clonal) proliferation of B- lymphocytes or T- lymphocytes which involves the lymph nodes, bone marrow and/or extranodal sites. "Both CLL and multiple myeloma are lymphoid cancers, which suggests that VSIR may play opposing roles depending on the hematopoietic lineage of cancer." (PMID 36394080, 2023).
mesothelioma (10 papers, 2020 to 2025). A usually malignant and aggressive neoplasm of the mesothelium which is often associated with exposure to asbestos. "VSIR is also strongly expressed in most mesothelioma cell lines." (PMID 40940864, 2025).
multiple myeloma (8 papers, 2021 to 2024). "VSIR expression is significantly prognostic in chronic lymphocytic leukemia (CLL), AML, and multiple myeloma." (PMID 36394080, 2023).
triple-negative breast carcinoma (8 papers, 2020 to 2024). An invasive breast carcinoma which is negative for expression of estrogen receptor (ER), progesterone receptor (PR), and human epidermal growth factor receptor 2 (HER2). "The roster of immune checkpoints encompasses an additional constituent, the V-set immunoregulatory receptor (also known as VISTA), which is identified as a crucial immune checkpoint that is influential in the management of various malignancies, particularly triple-negative breast cancer (TNBC)." (PMID 38397971, 2024).
chronic rhinosinusitis (2 papers, 2017 to 2019). Chronic form of sinusitis. "HLA-DRA has been associated with chronic rhinosinusitis with nasal polyps in previous studies and HLCS, BICD2, VSIR and SLC5A1 may be new targets for future research." (PMID 29253858, 2017). "Comparisons with data from expression quantitative trait loci showed the most skewed allelic distributions in cases with chronic rhinosinusitis with nasal polyps compared with controls for the genes HLCS, HLA-DRA, BICD2, VSIR and SLC5A1." (PMID 29253858, 2017). "Our study indicates that HLCS, HLA-DRA, BICD2, VSIR and SLC5A1 could be involved in the pathogenesis of chronic rhinosinusitis with nasal polyps." (PMID 29253858, 2017). "This study suggests that HLA-DRA as well as four additional genes; HLCS, VSIR, BICD2 and SLC5A1, which have not been previously identified as associated with chronic rhinosinusitis with nasal polyps, could be important for the development of this disease." (PMID 29253858, 2017).
basal cell carcinoma (1 paper, 2025). A carcinoma involving the basal cells. "Third, associations between higher genetically predicted VSIR expression and basal cell carcinoma (BCC) may suggest possible safety concerns with VISTA agonism." (PMID 41299435, 2025).
low grade glioma (1 paper, 2021). A grade I or grade II glioma arising from the central nervous system. "Overall, we observed significant association between IGSF10 and immune checkpoint genes such as CD200R1, VSIR, CD160, CD28, BTLA, and CD40LG in several tumors including low-grade glioma (LGG) and thyroid carcinoma (THCA)." (PMID 34351868, 2021).
myelodysplastic syndrome (1 paper, 2023). A clonal hematopoietic disorder characterized by dysplasia and ineffective hematopoiesis in one or more of the hematopoietic cell lines. "Importantly, VSIR expression is predictive of progression from myelodysplastic syndromes (MDS) patients into AML, suggesting its potential role during the very early stage of AML development and progression." (PMID 36394080, 2023).
synucleinopathy (1 paper, 2025). A neurodegenerative disease that is characterized by the abnormal accumulation of aggregates of alpha-synuclein protein in neurons, nerve fibers or glial cells. "Our observations at gene level, such as upregulation of chemokine and interferon response genes CCL2, IRF7, IL7R, and the immunomodulatory checkpoint gene VSIR, further reflect the complex immune environment within synucleinopathy appendixes." (PMID 41279937, 2025).
tumor (385 papers, 2015 to 2026). "We found that gap junction signaling pathways (ADCY8 and PPP1R9A) were upregulated and cell adhesion signaling pathways (VSIR and HLA-C) were downregulated, which is associated with tumor growth metastasis." (PMID 37511481, 2023). "We next investigated the potential of VISTA+ myeloid cells in mitigating RT response by examining the changes in MOC2 tumor growth following RT in VSIR WT (VSIRWTor VISTA+/+) and knockout (VSIRKOor VISTA−/−) mice." (PMID 40580480, 2025). "VSIR expression in tumor cells suppresses T cell proliferation in vitro and tumor infiltration in vivo." (PMID 40940864, 2025). "VSIR is also a B7 family immune checkpoint molecule expressed in multiple immune cell types (especially those of the myeloid lineage) and tumor cells." (PMID 40940864, 2025). "TNF-related interactions such as TNF_VSIR and CD74_MIF interactions are enriched in SN, exhibiting more inflammation-related tumor features." (PMID 37745301, 2023). "In both patient tumor samples and cancer cell lines we find that VSIR has the highest expression in AML out of all cancer types and, in AML, has the highest expression out of all other immune checkpoint genes." (PMID 36394080, 2023). "Upregulated VSIR on the tumor-infiltrating myeloid cells has been found to promote tumor growth through suppressing T cell immunity." (PMID 35493077, 2022). "The result demonstrated that PD-L1, PD1, CTLA4, B7-H3 and VSIR all played a role in regulating tumor immunity and were inversely correlated with the score." (PMID 33819918, 2021). "Analysis of the HNSCC-The Cancer Genome Atlas dataset confirmed a direct correlation between VISTA gene (VSIR) expression and MDSC abundance, reinforcing that VISTA is a prominent negative immune checkpoint on tumor-associated myeloid cells in HNSCC." (PMID 40580480, 2025). "In mice, VSIR is highly expressed in tumor‐infiltrating leukocytes." (PMID 36394080, 2023). "Previous studies have found that VSIR is widely involved in various physiological and pathological processes, including regulating peripheral tolerance, inducing T cell activation and differentiation, and mediating tumor immunity." (PMID 35493077, 2022). "Tumor hypoxia drives VSIR expression, which correlates significantly with HIF1A activity." (PMID 35659268, 2022). "In addition, the co-expression of VSIR on M2 macrophages and T cells was also detected in our tumor chip." (PMID 35493077, 2022). "In addition, VSIR was found to widely express on cancer cells, fibroblasts, macrophages, and T cells in many tumor types based on the single-cell sequencing analysis and co-express with M2 macrophage markers CD68, CD163 based on the immunofluorescence staining." (PMID 35493077, 2022). "However, the mechanism by which VSIR participates in tumor immunity in the pan-cancer tumor microenvironment remains unclear." (PMID 35493077, 2022). "Taking these data together, we speculate that VSIR plays a pivotal role in tumor immunity by affecting the functions of many inflammatory cells and can be used as a novel immunotherapy target in the process of tumor treatment in the future." (PMID 35493077, 2022). "Furthermore, higher expression of VSIR was discovered in C02 and C06 as well, indicating clusters with higher expression of PDCD1 and VSIR may tend to be downregulated by increased expression levels of tumor PD-L1." (PMID 33754038, 2021). "Targeting intracellular PD-L1 has been shown to promote antitumor immune responses in some mouse tumor models, and nuclear PD-L1 upregulates several genes involved in immunosuppression, including PDCD1LG2, BIRC3, RELB, and VSIR." (PMID 39996786, 2025). "Our results showed that the high-risk group with poor survival had a higher expression of T cell exhaustion markers, such as PDCD1/PD1, CTLA4, TIM3, LAG3, VSIR and TIGIT, which lead to tumor immune evasion." (PMID 36147509, 2022).
tumor (continued). "Finally, we analysed the expression of those genes in our GeoMx data, which revealed decreased levels of almost all genes, bar PVR, VSIR and NECTIN2, in the primary tumour, compared to healthy tissues." (PMID 41168392, 2025). "Additionally, tumor suppressive genes SAA1, VSIR, and BCL3 were also significantly upregulated in ACM samples." (PMID 36428692, 2022). "Additionally, the tumor suppressive genes SAA1, VSIR, and BCL3 were also significantly upregulated in ACM samples." (PMID 36428692, 2022). "Thus, as another HIF1A target that contributes to tumor immune escape, HIF1A upregulates VSIR expression under hypoxia." (PMID 35659268, 2022). "We found that tumor-infiltrating CD33high cells showed high gene expression levels of CD36, CD14, FUT4 (CD15), CD80, CD86, CSF1R and immune checkpoint ligand genes including CD274 (PD-L1), LGALS9 (galectin-9), PVR and VSIR." (PMID 33000418, 2021). "VSIR plays both negative and positive roles in tumor immunity." (PMID 35493077, 2022). "Under hypoxic conditions, HIF1A induces activation of target genes (PD-L1, CCL28, and GAL3ST1), resulting in immune cell apoptosis, and drives expression of the negative immune checkpoint regulator VSIR and MIC genes to evade immune surveillance and ultimately promote tumor immune escape." (PMID 35659268, 2022).